BCL2 (BCL2 apoptosis regulator)
Diseases named in the same sentence as BCL2 in open-access papers (continued):
Sharing a sentence is not in itself a finding about the gene and the disease.
cancer (continued). "Together, these datasets provide insights into the interactome landscape of BCL2, TDP-43, MDM2, and PTEN, and open potential avenues to explore their links to cancers and neurological disorders based on the newly found cell-type-specific interactions." (PMID 33972534, 2021). "We further show that ALS-implicated proteins were not enriched among BCL2 interactors found in any of the three cancer cell lines, confirming that a potential connection to ALS is a feature of the neuron-specific interaction partners of BCL2." (PMID 33972534, 2021). "Strikingly, in three out of 25 tested cancer types, survival of the high scoring group (high activation of FGF signalling and high expression of BCL-2 or MCL-1) was significantly decreased when compared to the low scoring group." (PMID 34772930, 2021). "Higher anticancer effects were obtained by developed liposomal curcumin powder than the other two tested medications in terms of pathology and the expression of various cancer-related markers such as VEGF, malondialdehyde, TNF-α, caspase-3, and BCL-2." (PMID 34451824, 2021). "The derivative reduced remarkably the expression of the BCL-2 in SNB-19, A549, and MDA-MB231 cancer lines, but in the Caco-2 cell line there was a slight increase." (PMID 33807874, 2021). "In this study, we investigate how an intracellular signalling network (STAT1, STAT3, Bcl-2 and BAX) regulates important cellular states, either anti-apoptosis or apoptosis of cancer cells." (PMID 34631119, 2021). "For instance, a BH4-domain-targeting peptide of Bcl-2, called Bcl-2/IP3 receptor disrupter-2 (BIRD-2), has been shown to have cell death-inducing effects in different cancer cell lines." (PMID 33918511, 2021). "The journey from the identification of BCL-2 dependence in AML to the successful development and clinical application of the BCL-2-specific inhibitor venetoclax is a triumph of modern cancer therapy." (PMID 33637708, 2021). "High levels of Bcl-2, XIAP and cIAPs are characteristic of many types of cancers and hence make these proteins attractive drug targets." (PMID 34943974, 2021). "However, little is known about the specific role of BCL2 in different human cell types, and insights into its overlapping and differential interaction partners in neurons compared to cancer cell lines could generate actionable biological hypotheses of therapeutic relevance." (PMID 33972534, 2021). "BCL2 and BCLXL play critical roles in apoptosis and cancer development and they can be regulated by GSK-3." (PMID 33917370, 2021). "Several other genes, such as BCAT1, BCL2, and ATF6, are related to prognosis in other types of cancers." (PMID 34771630, 2021). "Given its crucial role in escaping apoptosis in cancer, efforts have been made to develop BH3-mimetic agents and in particular BCL-2 inhibitors." (PMID 34830763, 2021).
cancer (continued). "Several oncogenic targets of STAT3 have been recently identified such as c-myc, c-Jun, PLK-1, Pim1/2, Bcl-2, VEGF, bFGF, and Cten, and inhibitors of STAT3 have been developed for cancer prevention and treatment." (PMID 33435349, 2021). "More specifically, these studies show that CD36 can promote the activation of the MAPK signaling pathway, upregulate protein expression of Bcl2 and cyclin D1 and engage with the TGF-β signaling for epithelial to mesenchymal transition (EMT) by cancer cells." (PMID 34215227, 2021). "KRIBB11 effectively decreased the HSP70/BAG3/BCL2 and EGFR/MET/AXL proteins, leading to apoptosis of resistant cancer cells." (PMID 34203709, 2021). "As an important oncogene, Bcl-2 can inhibit cell apoptosis by inhibiting the activation of apoptosis proteins (such as BAX and BAK), thereby promoting the survival of cancer cells." (PMID 33778070, 2021). "For example, BCL2L2 (protein 2 similar to BCL2, also known as BCL-w), myeloid leukemia 1, and BCL2 are observed to be overexpressed in various kinds of cancers, leading to carcinogenesis and apoptosis inhibition." (PMID 34090463, 2021). "As we know, a high Bax:Bcl-2 ratio induces apoptosis in cancer cells, thus piperine can induce apoptosis in HL60 by regulating the level of Bax and Bcl-2 proteins." (PMID 35069196, 2021). "Persistent activation of STAT3 also contributes to tumorigenesis by upregulating the transcription of genes that control cancer cell survival (e.g., cyclins and c-MYC), resistance to apoptosis (e.g., BCL2, MCL1), and cell cycle activation." (PMID 34944848, 2021). "TW-37, a Bcl-2 inhibitor, exhibited synergistic results against SCC and cancer-connected endothelial cells in vivo and in vitro combined for cisplatin." (PMID 34638779, 2021). "Among the various strategies that have been proposed to block Bcl-2, BH3-mimetics have appeared as a novel group of compounds thanks to their favorable effects on many cancers within several clinical settings." (PMID 34638779, 2021). "The Bcl-2 agonist of cell death (BAD) is a pro-apoptotic protein, which can be inactivated by its phosphorylation in many cancers, so blocking BAD phosphorylation can promote cell apoptosis." (PMID 34248628, 2021). "High expression of BCL-2/BCL-XL and overexpression of caspase-3 were found to inhibit apoptosis in multiple myeloma and resulted in resistance of the cancer cells to bortezomib." (PMID 34502361, 2021). "Combination of melatonin with ER stress inducer tunicamycin increases the sensitivity of cancer cells to apoptosis through inhibiting the expression of COX-2 and increasing the Bax/Bcl-2 ratio and CHOP levels." (PMID 33789681, 2021). "Knockouts of some “cancer drivers” of DLBCL, including BCL2, BCL6, NFKBIA and CD70, showed only modest promotional effects on cell proliferation." (PMID 33911074, 2021). "Bcl-2 is well-known for being a key regulator of the progression of apoptosis and MDR in multiple types of cancer." (PMID 35054564, 2021). "PCC1 was shown to decrease the level of BCL-2 but increase expression of the regulator BAX and activities of caspases 3 and 9 in cultured cancer cells, thus potentially generating anticancer effects through induction of apoptosis." (PMID 34873338, 2021). "As indicated by western blot analysis, treatments with T-96 resulted in more Cleaved-PARP1 and Bax proteins, but decreased expression of Bcl2, Survivin and PARP1 in the cancer cells when compared with the control group." (PMID 34093803, 2021). "We use Genoppi to analyze 16 cell-type-specific protein interaction datasets of four proteins (BCL2, TDP-43, MDM2, PTEN) involved in cancer and neurological disease." (PMID 33972534, 2021).
cancer (continued). "Increased expression of MCL-1 is a common response to long-term treatment with selective inhibitors of BCL-2/BCL-XL.Therefore, available evidences indicate that MCL-1 is an attractive target for cancer treatment." (PMID 33883020, 2021). "Among members of the basic circuitry for evasion of the apoptotic process in cancer, BAX and BCL-2 are tightly coregulated, inhibiting mitochondrial function." (PMID 33531986, 2021). "Apoptotic pathways in cancer cells are disrupted by downregulation of BAX and BAK or upregulation of anti-apoptotic B-cell lymphoma-2 (BCL-2) proteins." (PMID 34830916, 2021). "Targeting the Bcl-2 rheostat with ABT-263, therefore, is a particularly promising approach to overcome radioresistance of cancer cells exposed to acute or chronic hypoxia with intermittent reoxygenation." (PMID 34257274, 2021). "Co-targeting metabolism and apoptosis by inhibiting both BCL-2 and OXPHOS complex-I has recently been proven a highly potent strategy to kill apoptosis-refractory and OXPHOS-reliant cancer cells." (PMID 34283054, 2021). "Accordingly, we find in certain cancer types a correlation between FGF-signalling, BCL-2 expression and worse prognosis." (PMID 34772930, 2021). "In other cancer models, YAP has been shown to transcriptionally upregulate Bcl2 family pro-survival proteins, such as Bcl2 and Bcl-XL, to promote therapy resistance." (PMID 34572875, 2021). "Suggestive of its relevance in vivo, we find that in certain cancer types there is a correlation between FGF-signalling, anti-apoptotic BCL-2 protein expression and poor prognosis." (PMID 34772930, 2021). "Several studies have shown that miR-1915-3p modulates multidrug resistance, anti-apoptosis and stem cell differentiation by targeting BCL2 apoptosis regulator (BCL2), prominin 1 (PROM1) and paired box 2 (PAX2) in multiple types of cancers." (PMID 34774019, 2021). "However, the molecular mechanism by which Bcl-2 protein in its mitochondrial outer membrane location protects cells remains elusive due to the absence of structural insight; and current strategies to therapeutically interfere with these Bcl-2 sensitive cancers are limited." (PMID 33800399, 2021). "This agrees with our study and gives insights into the other role of the ANE in cancers, as induction of apoptotic signaling by ANE treatment was also found, as evidenced by an increase in c-PARP and a decrease in the Bcl-2 molecule." (PMID 34522171, 2021). "It has been confirmed that Cur induces apoptosis of various cancer cells including CRC cancer cells in response to the expression of Bcl-2 and Caspase-3, which is related to the sensitivity of CRC cancer cells to the chemotherapy." (PMID 34380471, 2021). "Directly targeting anti-apoptotic proteins like Bcl-2, IAPs and FLIP or pro-apoptotic effectors like DR4/5 are attractive anti-cancer strategies." (PMID 34073507, 2021). "Low doses of BTZ enhanced the anti-cancer effect induced by the low dose of BGB-3111 by downregulating the expression levels of PARP and Bcl-2 and increasing the expression levels of cleaved PARP and cleaved caspase-9." (PMID 34508613, 2021). "Compound 42 presented proapoptotic effects in cancer cell lines, inducing cell cycle arrest at the G0/G1 phase, increased p21 and BAX, and decreased BCL-2 antiapoptotic proteins." (PMID 33802144, 2021).
cancer (continued). "Whilst BCL-XL, MCL-1 and BCL-2 have received most of the attention in oncology drug development, the lesser discussed pro-survival BCL-2 proteins, BCL-W and BFL-1, also have important roles in cancer." (PMID 34581776, 2021). "Bcl-2 and CCNE1 were famous factors contributing to cell proliferation in nearly all kinds of human cancers." (PMID 34660260, 2021). "ARTS-mimetics provide a promising novel platform for developing highly specific and potent anti-cancer drugs by targeting XIAP-and Bcl-2 for degradation." (PMID 34943974, 2021). "Resistance to the inhibition of BCL2 was overcome by inhibiting MDM2; cancer cells can become resistant to BCL2 inhibition by increasing the production of other anti-apoptotic proteins, such as MCL-1." (PMID 35008180, 2021). "Positive SSTR2 expression in cancer cells was present in 26 out of 52 IHCC cases (50.0%) and positive Bcl2 expression in cancer cells was present in 19 (36.5%)." (PMID 33962620, 2021). "Reports in several cancers explained that activated PI3K/AKT signaling is involved in the downregulation of tumor suppressor PTEN and upregulation of anti-apoptotic factor BCL-2, respectively." (PMID 34632072, 2021). "Using this approach, we identified several cancer types that displayed a correlation between FGF activation and BCL-2 and/or MCL-1 expression." (PMID 34772930, 2021). "At least in part, such effects are orchestrated through common signaling pathways comprised of NF-κB, bcl-2, MAPK/ERK, PARP, and caspase 3; see also under “Molecular Pathways Affected by Mn Porphyrins in Normal and Cancer Cell”." (PMID 33815656, 2021). "Based on literature information, oncogenic states are defined as abnormal marker combinations, e.g., expression of BCL6 in combination with BCL2 and/or MYC is an aggressive cancer state." (PMID 34829885, 2021). "Here, we observed that SPP (0–500 μg/mL) treatment increased Bax protein expression levels and decreased Bcl-2 protein expression levels in both HL-60 and CCRF-SBA cancer cells in a dose-dependent manner." (PMID 33086647, 2020). "In the current study, we observed that treatment of cancer cells with DCM and MeOH extracts of S. amplexicaulis led to a decrease in the mRNA expression levels of Bcl-2 and increases in p-53, caspase-3, caspase-9, and Bax." (PMID 33122979, 2020). "This has led to the recent development of selective BCL2 inhibitors, such as ABT-263 (navitoclax) and ABT-199 (venetoclax), for cancer treatment." (PMID 33239070, 2020). "The anti-apoptotic proteins BCL-2, MCL-1 and BCL-xL prevent MOMP via direct interactions with the pro-apoptotic proteins and have been shown to protect cancer cells from stress stimuli induced by chemotherapies." (PMID 33080792, 2020). "The continuous activation of the NF-κB pathway can increase antiapoptotic gene Bcl-2 expression, upregulate expression of proliferation-related proteins CDK1 and CDK2, and promote cell cycle, thus promoting cancer cell proliferation." (PMID 32337232, 2020). "The augmented level of c-FLIP, Bcl-2 and Mcl-1 has been noted in NSCLC, posing present and future challenges in cancer therapy." (PMID 32069989, 2020). "One of the main mechanisms for cancer cells escaping apoptosis induction is through over-expression or anti-apoptotic proteins, such as the BCL-2-protein family, of which BCL-2 is the prototype." (PMID 32337074, 2020). "The expression of Bax in cancer cells increased significantly (P < 0.05) after magnetic hyperthermia treatment (MNPs + AMF) compared to that in control group; Furthermore, Bcl-2 expression decreased significantly (P < 0.05) in the group of MNPs + AMF." (PMID 33266461, 2020). "Subsequently, ABT-263 (the upgraded products of ABT-737), BM 1197, S44563, BCL2 32, and AZD4320, as inhibitors of BCL2 and BCL-XL, were also reported to inhibit cancer progression successively." (PMID 33126914, 2020).
cancer (continued). "The attached siRNA, targeting the apoptosis inhibitor protein Bcl-2, was covered by a layer of PEG-Poly(acrylic acid)-folic acid to prolong circulation and enhance cancer cell targeting." (PMID 32532030, 2020). "The phenotype of cancer cells shows variable expression of CD20 and presents CD19+, CD79a+, CD10-, BCL2+, PAX5+, BCL6-, and MUM-1/IRF-4+." (PMID 32528871, 2020). "The phenotypes of cancer cells are CD20+, BCL2+, and IRF4/MUM-1+ with active proliferation (MIB-1/Ki 67++)." (PMID 32528871, 2020). "Given that MAPK pathway cross‐talks with Akt pathway in the regulation of cancer development, it is plausible that CFTR modulates Akt/Bcl2 via activation of MAPK." (PMID 32463592, 2020). "Cell proliferation and apoptosis have been reported to be key processes of cancer development, characterized by potential targets of proliferation-related protein PCNA, antiapoptotic protein Bcl-2, and proapoptotic protein Bax." (PMID 32051829, 2020). "Significance of AR expression was correlated with prognostic biomarkers including cancer stem cell markers (CD44, CD24, and ALDH1), basal markers (CK5, CK14, and nestin), proliferation marker (ki-67), apoptotic marker (Bcl-2), and COX-2." (PMID 32850312, 2020). "A myriad of intracellular proteins involved in cancer progression, such as the central oncoproteins KRAS, BCL-2, and HDM2, remain difficult to target pharmacologically." (PMID 31636382, 2020). "The cellular experiments showed that HD-SB significantly induced cancer cell apoptosis, decreased p-EGFR, HSP90 and bcl-2 expressions, and increased PPARγ, bax, cleaved caspase 3, cleaved PARP, p-AKT, and p-PI3K expressions compared with HD or SB treatment." (PMID 32265701, 2020). "For example, in urologic cancer, common genes regulated by prognosis-alternative miRNAs such as BCL2, EGFR, KIT, PDGFRA, and VEGFA, have been validated as anti-cancer drug targets previously." (PMID 32523951, 2020). "Herein, apoptosis was induced in human breast MCF-7 cancer cells by modulating the expression of BAX, CASPASE-3, SURVIVIN, and BCL-2 genes." (PMID 32020890, 2020). "In this context, a powerful model to eliminate senescent cells is the use of the established BCL‐2/BCL‐XL inhibitor, ABT‐263 (navitoclax) as a senolytic adjuvant in cancer therapy." (PMID 32652830, 2020). "Normally, triggering mitochondrial apoptosis in cancer cell lines by both prodigiosin and PU-H71 necessitates BAX activation and downregulation of BCL2 to initiate cytochrome c release." (PMID 32895397, 2020). "By RNA sequencing analysis of a pan-cancer cohort comprising >1500 patients and subsequent prediction of protein activity, BCL-XL was identified as the only antiapoptotic BCL-2 protein that is overactivated in CRC." (PMID 33070156, 2020). "For example, a small molecule, named ABT-737, was issued as a potential inhibitor of BCL-2 and BCL-XL, which occupies their BH3-binding domain and further triggers apoptosis in diversified cancer types." (PMID 32328476, 2020). "For example, both ABL1 and BCL2 genes were validated as oncogenes, actionable genes, essential genes, genes in CGC, potential drug targets, and also contributed to hallmarks of cancer." (PMID 33240468, 2020). "It was found that HD-SB treatment significantly decreased bcl-2 expression; increased bax, cleaved caspase 3, cleaved PARP, p-AKT, and p-PI3K; and finally induced cancer cell apoptosis." (PMID 32265701, 2020). "Gossypol directly interacts with and inhibits anti-apoptotic factors, BCL-2 and BCL-2-like protein 1 (BCL2L1, also named BCL-XL), enacting apoptotic cell death in cancer." (PMID 33066509, 2020).